CPT1C (carnitine palmitoyltransferase 1C)
Description:
Palmitoyl thioesterase specifically expressed in the endoplasmic reticulum of neurons. Modulates the trafficking of the glutamate receptor, AMPAR, to plasma membrane through depalmitoylation of GRIA1. Also regulates AMPR trafficking through the regulation of SACM1L phosphatidylinositol-3-phosphatase activity by interaction in a malonyl-CoA dependent manner (By similarity). Binds malonyl-CoA and couples malonyl-CoA to ceramide levels, necessary for proper spine maturation and contributing to systemic energy homeostasis and appetite control. Binds to palmitoyl-CoA, but does not have carnitine palmitoyltransferase 1 catalytic activity or at very low levels.
Synonyms: CPTI-B; CPT I-C; CATL1; FLJ23809; CPTIC; CPT1P; CPT1-B; SPG73
Tractability: Antibody: UniProt predicts a signal peptide or a membrane-spanning region. PROTAC: its protein half-life has been measured.
Gene: Protein-coding gene on chromosome 19 (49,690,898 to 49,713,731, forward strand). Ensembl gene ENSG00000169169.
Subcellular location: Cell projection, dendrite; Cell projection, axon; Endoplasmic reticulum membrane
Gene Ontology:
Molecular function: palmitoyl-(protein) hydrolase activity; protein binding; carnitine O-palmitoyltransferase activity; acyltransferase activity; catalytic activity
Biological process: carnitine metabolic process; fatty acid metabolic process; macromolecule depalmitoylation; regulation of postsynaptic membrane neurotransmitter receptor levels
Cellular component: endoplasmic reticulum; endoplasmic reticulum membrane; axon; dendrite; mitochondrion; AMPA glutamate receptor complex; glutamatergic synapse; postsynapse
Genetic constraint (gnomAD): Loss-of-function variants: 60 observed, 95.6 expected, observed/expected ratio (o/e) 0.63, 90% interval 0.51 to 0.78. The upper end of that interval is the gene's LOEUF score, 0.78, which puts it in group 3 of 6, group 1 being the genes least tolerant of losing a copy. Missense variants: 971 observed, 1,074.6 expected, observed/expected ratio (o/e) 0.9, 90% interval 0.86 to 0.95. Synonymous variants: 468 observed, 454.31 expected, observed/expected ratio (o/e) 1.03, 90% interval 0.95 to 1.11.
Gene-disease validity (ClinGen):
ClinGen rates the evidence that CPT1C causes each of these diseases.
hereditary spastic paraplegia (autosomal dominant): Limited. Hereditary spastic paraplegias (HSP) comprise a genetically and clinically heterogeneous group of neurodegenerative disorders characterized by progressive spasticity and hyperreflexia of the lower limbs.
Homologues: Orthologues: chimpanzee CPT1C (99% identical), macaque CPT1C (97% identical), dog CPT1C (90% identical), guinea pig CPT1C (87% identical), mouse Cpt1c (83% identical), rat Cpt1c (82% identical), pig CPT1C (78% identical), Drosophila melanogaster whd (42% identical), Caenorhabditis elegans cpt-1 (40% identical), Caenorhabditis elegans W03F9.4 (32% identical). Paralogues in human: CPT1A (53% identical), CPT1B (51% identical), CRAT (24% identical), CHAT (23% identical), CPT2 (23% identical), CROT (21% identical).
Diseases named in the same sentence as CPT1C in open-access papers:
CPT1C is named in the same sentence as 61 diseases in open-access papers, as found by Europe PMC text mining. Sharing a sentence is not in itself a finding about the gene and the disease. The quoted sentences say what the papers report.
breast carcinoma (16 papers, 2015 to 2025). "CPT1C overexpression in breast cancer (MCF7) and papillary thyroid carcinoma (KTC-1) cell lines has been reported to promote survival in response to hypoxia or glucose depletion." (PMID 36693836, 2023). "Consistently, clinical validation reveals that high CPT1C is observed in breast cancer patients with metastasis and is correlated with poor overall, disease-free, progression-free, and disease-specific survival in BLBC patients." (PMID 35936710, 2022). "Compared to normal tissue, clinical tissue samples from patients with multiple cancers, especially pancreatic cancer and breast cancer, showed high CPT1C expression (37,38, and unpublished data)." (PMID 32641987, 2020). "As a member of the CPT family, CPT1C has emerged as a potential therapeutic target in various types of cancer, such as breast cancer and neuroblastoma 8,10,36." (PMID 32641987, 2020). "CPT1B is expressed in muscle, heart, and adipose tissue and CPT1C in neurons, whereas CPT1A is more widely expressed and has been previously implicated as a therapeutic target in breast cancer cells." (PMID 29596410, 2018). "The same study highlighted that CPT1C downregulation led to breast cancer stromal remodeling and anthracycline resistance, suggesting that CPT1C could serve as a novel predictive biomarker for breast cancer chemotherapy." (PMID 39596847, 2024). "Subsequently, more and more studies have demonstrated that CPT1C plays an important pro-carcinogenic role in a variety of cancers, such as colorectal, endometrial, hepatocellular, gastric, esophageal squamous cell, and breast cancers." (PMID 39596847, 2024). "Moreover, patients with gastric cancer, hepatocarcinoma, and basal-like breast cancer with high CPT1C expression were reported to experience significantly shorter overall survival compared to patients with low CPT1C expression." (PMID 36693836, 2023). "Both in the current and previous studies, the breast cancer cell line MDA-MB-231 and the pancreatic cancer cell line PANC-1 were used for the specific expression of CPT1C and miR-1291 in pancreatic and breast cancer tissues." (PMID 32641987, 2020). "Since CPT1A, CPT1B, and CPT1C belong to the CPT family, we also compared the clinical relevance of CPT1A, CPT1B, and CPT1C in total breast cancer patients and patients with various subtypes of breast cancer." (PMID 35936710, 2022). "CPT1C silencing drives serosa remodeling, leading to chemotherapy resistance to doxorubicin in BCCs, and the low expression of CPT1C is a predictive marker for poor prognosis in HER2-positive breast cancer and TNBC patients treated with anthracycline-based neoadjuvant chemotherapy." (PMID 40256431, 2025). "Additionally, in total breast cancer patients, the miR-200c-Low cohort exhibits a higher expression of CPT1C, and a moderate negative correlation between the expression of CPT1C and miR-200c was also revealed by Spearman correlation analysis (R=0.18, P<0.0001)." (PMID 35936710, 2022).
Obesity (15 papers, 2010 to 2025). Accumulation of substantial excess body fat. "The authors suggest a ghrelin/CPT1C/ceramide axis is important for the understanding and treatment of obesity, in which CPT1C KO mice had the orexigenic action of ghrelin totally abolished." (PMID 34069652, 2021). "For example, miR-615-3p interacts with CPT1C in obesity and regulates ACOX1 and ALDH1B1 in uterine cancer." (PMID 33121472, 2020). "One study found that Cpt1c+/− mice are smaller than WT mice even under a CHD condition and they are susceptible to insulin resistance, obesity, and hepatosteatosis under a HFD condition." (PMID 25309812, 2014). "Paradoxically, when high fat diet was given to CPT1c KO mice, they exhibited diet-induced obesity which ultimately resulted in a diabetic phenotype." (PMID 23098614, 2012). "Overall, these data indicate that, in addition to formerly reported mechanisms, ghrelin also induces food intake through the regulation of hypothalamic CPT1C and ceramide metabolism, a finding of potential importance for the understanding and treatment of obesity." (PMID 34069652, 2021). "Transgenic CPT1c mice (CPT1c-TgN), on the other hand, which allowed conditional expression of CPT1c in a tissue-specific manner via cre-lox recombination, showed enhanced expression of CPT1c and they were protected from diet-induced obesity even on a high-fat diet." (PMID 23098614, 2012). "Future studies can be expected to further provide information on such molecular mediators, e.g., the recently characterized CPT1C, as these may represent a more specific target for the regulation of endocannabinoid levels in the context of obesity and other metabolic disorders." (PMID 34718828, 2021).
gastric cancer (8 papers, 2022 to 2025). A primary or metastatic malignant neoplasm involving the stomach. "For instance, cancer-associated fibroblasts expressing CPT1C in gastric cancer release IL-6, which promotes immunosuppressive M2 macrophage polarization." (PMID 41219902, 2025). "A direct transcriptional upregulation of CPT1C by the hypoxia-inducible factor HIF1α was similarly found in gastric cancer and was associated with the malignant proliferative behavior of gastric cancer cells." (PMID 39596847, 2024). "Clinical data indicate that gastric cancer patients with high CPT1C+ fibroblast infiltration exhibit reduced responsiveness to immunotherapy." (PMID 41219902, 2025). "In addition, CPT1C promotes gastric cancer drug resistance by enhancing FAO and subsequently upregulating the mRNA expression levels of gastric cancer stem cell markers (CD44, EpCam, and Lgr5)." (PMID 41219902, 2025). "In contrast, in gastric cancers that developed ovarian metastases, CPT1C was similarly found to be able to promote the invasive growth of gastric cancer cells toward the ovarian site by upregulating the FAO rate and was able to increase the stemness characteristics of the cells." (PMID 39596847, 2024). "Besides its role in facilitating tumor cell proliferation and survival, CPT1C has also been reported to play a supporting role in promoting gastric cancer ovarian metastasis, hepatocellular carcinoma metastasis and colorectal cancer cell metastasis." (PMID 38783346, 2024). "A new immunosuppressive subpopulation of fibroblasts exists in gastric cancer, which can exclusively overexpress CPT1C and secrete the pro-inflammatory cytokine IL-6 to interfere with the immunosuppressive function of macrophages in gastric cancer, thereby exerting a pro-cancer effect." (PMID 39596847, 2024). "In addition, a single-cell study of gastric cancer identified a population of CAFs expressing carnitine palmitoyltransferase 1C (CPT1C) that secreted IL-6 to facilitate the development of M2-like TAMs, thereby promoting the formation of an immunosuppressive TME." (PMID 40453088, 2025). "In addition, a significantly different expression of other genes relevant for tumor progression could be found, e.g., Carnitine palmitoyltransferase 1 C (CPT1C), which promotes tumor growth and drug resistance, being reported for gastric cancer." (PMID 36230659, 2022). "Functional assays showed that overexpression of CPT1C promoted the migration and invasion of GC cells and increased the expression of gastric cancer stem cell (GCSC) marker through up-regulating FAO rate." (PMID 35593464, 2022). "In addition, Gaoet al. reported that CPT1C could promote the ovarian metastasis of gastric cancer." (PMID 37078750, 2023). "In gastric cancer, FAO mediated by CPT1C was proven to be an important factor promoting cell proliferation." (PMID 37078750, 2023).
colorectal cancer (6 papers, 2020 to 2025). A primary or metastatic malignant neoplasm that affects the colon or rectum. "Silencing of mitochondrial CPT1-C in unstressed colorectal cancer causes intracellular fatty acid accumulation, lipid peroxidation, and decreased ATP levels." (PMID 33291682, 2020). "Carnitine palmitoyltransferase 1C (CPT1C), a rate-limiting enzyme in FAO, mainly functions to catalyze fatty acid carnitinylation and guarantee subsequent entry into the mitochondria for FAO in colorectal cancer (CRC)." (PMID 37078750, 2023). "Remarkably, colorectal cancer cells not only express CPT1-A, they also express CPT1-C." (PMID 33291682, 2020).
pancreatic cancer (6 papers, 2020 to 2024). "Recently, it was found that CPT1C can act as a novel target gene of ERRα and regulate the proliferation, metabolism, and tumorigenesis of breast and pancreatic cancer cells through the direct regulatory network formed by miR-1291, ERRα, and CPT1C." (PMID 39596847, 2024). "ESRRA was identified as a prominent differentially expressed gene in both breast and pancreatic cancer samples, and estrogen-related receptor α (ERRα) was found to link miR-1291 and CPT1C." (PMID 32641987, 2020). "Since both miR-1291 and CPT1C were identified as tumor biomarkers in pancreatic cancer 1,2,11 and both are closely related to tumor metabolism 4,5,12, the assumption was made that they may be mechanistically linked in their impact on cancer." (PMID 32641987, 2020). "PPARα was found to induce carnitine palmitoyltransferase 1C (CPT1C) in a breast and a pancreatic cancer cell line, leading to the activation of cell proliferation." (PMID 35954274, 2022). "miR-1921 form a regulatory axis with ER that controls the proliferation and cell metabolism by targeting the expression of Carnitine palmitoyltransferase 1C (CPT1C) in breast and pancreatic cancer." (PMID 34722255, 2021). "IL-8 was negatively correlated (but without statistical significance) with CPT1C mRNA expression in pancreatic cancer patients, further supporting enhanced SASP in low-CPT1C-induced senescent vector PANC-1 cells." (PMID 32289751, 2020).
lung carcinoma (5 papers, 2013 to 2024). "Kaplan-Meier analysis confirms the same poor survival in patients with ovarian or lung cancer with high CPT1C expression, pointing to CPT1C as a prognostic marker for several tumor types." (PMID 36693836, 2023). "Fatty acid synthase (FASN) and carnitine palmitoyltransferase 1c (CPT1C) are FA metabolism enzymes that have also been reported to be elevated in lung cancer." (PMID 23936004, 2013).
papillary thyroid carcinomas (5 papers, 2020 to 2023). "Other authors subsequently reported higher CPT1C expression (mRNA or protein levels) in other types of tumors, e.g., papillary thyroid carcinomas and hepatocellular carcinomas than in normal tissues." (PMID 36693836, 2023). "Moreover, CPT1C promotes cancer cell growth and metastasis in papillary thyroid carcinomas under conditions of metabolic stress." (PMID 33282950, 2020).
Spastic paraplegia (5 papers, 2019 to 2025). Complete loss of the ability to move the lower limbs accompanied by spasticity of the lower limbs. "Cpt1c (carnitine palmitoyltransferase 1c) is mainly expressed in neurons and has been shown to be associated with spastic paraplegia, a genetic disorder that causes leg stiffness and change in gait." (PMID 31722663, 2019). "Disorders associated with pathogenic CPT1C variants cause lethal spastic paraplegia (OMIM #616282)." (PMID 34915862, 2021). "Spastic paraplegia, which is exclusive to CPT1C and has nothing in common with CPT1A deficiency, is most likely caused by a dominant genetic variant in CPT1C." (PMID 37033619, 2023).
glioma (4 papers, 2014 to 2025). A benign or malignant brain and spinal cord tumor that arises from glial cells (astrocytes, oligodendrocytes, ependymal cells). "In glioma (GLIOMA_GSE103224), seven cell populations were identified, with CPT1C predominantly expressed in nerve cells and oligodendrocyte precursor cells." (PMID 41219902, 2025). "However, recent research showed that CPT1C located in both the nucleus and the cytoplasm in glioma cells." (PMID 35057851, 2022). "It is noteworthy that recent studies report an aberrant expression of CPT1C in gliomas." (PMID 25698923, 2014).
hepatocellular carcinoma (3 papers, 2022 to 2024). A malignant tumor that arises from hepatocytes. "Nonetheless, in hepatocellular carcinoma, a direct target binding site for MiR-377-3p exists in the 3′UTR region of CPT1C, which affects the downstream FAO rate through direct target inhibition, thereby influencing the malignant biological behavior of hepatocellular carcinoma." (PMID 39596847, 2024).
hereditary spastic paraplegia (3 papers, 2019 to 2025). "The first pathogenic variant of CPT1C has recently been reported in humans, and CPT1C has been identified as the gene responsible for hereditary spastic paraplegia." (PMID 36818560, 2023). "This regulation seems of special importance in neurons with long axons, such as corticospinal motor neurons, since individuals with mutated CPT1C develop hereditary spastic paraplegia." (PMID 31868590, 2019). "Interestingly, the unique two CPT1C mutations described in humans to date have been associated with hereditary spastic paraplegia (HSP)." (PMID 31868590, 2019). "Autosomal‐dominant variants in the CPT1C gene have been associated with hereditary spastic paraplegia type 73 (SPG73), which typically presents with slowly progressive lower limb weakness and spasticity and is therefore considered a pure form of hereditary spastic paraplegia." (PMID 39737739, 2025).
melanoma (3 papers, 2020 to 2022). A malignant, usually aggressive tumor composed of atypical, neoplastic melanocytes. "Furthermore, the TCGA melanoma database analysis identified a prognostic signature containing CAV1 (caveolin 1), CD36 and CPT1C (carnitine palmitoyltransferase 1C), members of which are responsible for fatty acid uptake and metabolism." (PMID 35628196, 2022).
sarcoma (3 papers, 2019 to 2023). A usually aggressive malignant neoplasm of the soft tissue or bone. "Subsequent CPT1C mRNA expression studies in a wide array of tumour types showed that CPT1C is also highly expressed in brain tumours and several sarcomas." (PMID 36674468, 2023). "Reilly and Mak reported unusual and enhanced expression of CPT1C in brain cancers and several sarcomas of soft-tissues and lung." (PMID 36230659, 2022).
Alzheimer disease (2 papers, 2021 to 2024). A progressive, neurodegenerative disease characterized by loss of function and death of nerve cells in several areas of the brain leading to loss of cognitive function such as memory and language. "This study aimed to investigate the role of CPT1C in Alzheimer’s disease (AD) and its underlying mechanism." (PMID 34424821, 2021).
Ewing sarcoma (2 papers, 2019 to 2024). A small round cell tumor that lacks morphologic, immunohistochemical, and electron microscopic evidence of neuroectodermal differentiation. "Among the three subtypes of CPT1, elevated levels of CPT1C mRNA have been reported in specific cancer types, particularly in STSs, with Ewing’s sarcoma and bone sarcoma following in rank." (PMID 38786727, 2024).
metastatic disease (2 papers, 2016 to 2022). "Furthermore, we observed gain of CPT1C and CYP2E1 expression which may be indicative of increased mitochondrial β-oxidation and microsomal ω-oxidation, respectively, in metastatic tumors." (PMID 26725848, 2016). "However, on day 98, the metastatic signal was detectable on CPT1C-KD mice instead of control mice, indicating when CPT1C-KD mice began to develop metastasis, control mice had already died from metastatic disease, and those who still survived were control mice without metastatic burden." (PMID 35936710, 2022).